FGF23 (fibroblast growth factor 23)
Diseases named in the same sentence as FGF23 in open-access papers (continued):
Sharing a sentence is not in itself a finding about the gene and the disease.
chronic kidney disease (continued). "Data reported that increased levels of FGF23 in patients with chronic kidney disease may be responsible for left ventricular hypertrophy." (PMID 38139126, 2023). "Proinflammatory cytokines such as TNFα, IL-1β, and IL-6 are potent stimuli for the FGF-23 secretion by osteocytes and have been demonstrated to play a role in upregulating intact FGF23 in experimental models in vivo of both acute kidney injury and chronic kidney disease." (PMID 37893926, 2023). "Consistent with these pre-clinical observations, in both the adult Chronic Renal Insufficiency Cohort (CRIC) study and the pediatric Chronic Kidney Disease in Children (CKiD) study, higher circulating FGF23 concentrations were independently associated with left ventricular hypertrophy." (PMID 35237863, 2022). "Finally, this article mentioned that measurement of FGF-21 and FGF-23 was useful for detecting chronic kidney disease (CKD) and its complications, such as cardiovascular disease and metabolic bone disease." (PMID 35574015, 2022). "In an animal study of cats with chronic kidney disease, a negative association between serum magnesium concentration and FGF23 was found, which was independent of calcium, phosphate, and PTH." (PMID 35629904, 2022). "So, FGF23 has been recognized as an important prognosis biomarker of chronic kidney disease." (PMID 35801203, 2022). "In addition, elevated FGF-23 level has been shown to be an independent predictor of death in patients with chronic kidney disease (CKD) and ESRD." (PMID 34297744, 2021). "Importantly, FGF23 levels start increasing early in the course of chronic kidney disease (CKD) and reach extremely high levels in patients on dialysis." (PMID 33000285, 2021). "The FGF-23 pathway may represent an additional link between the development of acute and chronic kidney disease." (PMID 34063052, 2021). "Elevated FGF-23 is associated with negative health consequences including inflammation and is an early marker for chronic kidney disease." (PMID 33888157, 2021). "Although the reason is still unclear, several reports revealed that FGF23 is a strong predictor of adverse cardiovascular outcomes in patients with chronic kidney disease (CKD), suggesting a contribution of FGF23 to type 4 CRS (chronic renal dysfunction leading to cardiovascular dysfunction)." (PMID 33460402, 2021). "FGF-23 levels rise as renal function declines, and higher levels are strongly associated with increased risks of cardiovascular disease (CVD), heart failure, and progression to end-stage renal disease (ESRD)." (PMID 34297744, 2021). "Interestingly, a cross-over study involving chronic kidney disease stage 3 and 4 demonstrated that patients who consumed a plant-based diet had lower levels of FGF23 and phosphorous levels." (PMID 34199304, 2021). "In this study, we analysed FGF23, Klotho, 1,25-dihydroxyvitamin D3, 25-hydroxyvitamin D, parathormone, Calcium and Phosphate levels of haemodialysis patients in order to investigate the nature of the mineral metabolism disruption in chronic kidney diseases." (PMID 33776565, 2021). "Furthermore, knockdown of Fam20C in cells promotes FGF23 mRNA expression, and elevated levels of serum FGF23 contribute to cardiovascular complications and increased mortality in patients with chronic kidney disease." (PMID 33759783, 2021). "Accordingly, FGF-23 may be a potential target for regulating cardiac fibrosis, especially in patients with chronic kidney disease who generally have higher circulating FGF-23 levels." (PMID 35008591, 2021). "Chronic kidney disease reduces DMP1 expression in osteocytes, while DMP1 supplementation prevents osteocyte apoptosis, lowers FGF23 expression, increases serum phosphate, and prevents the development of left ventricular hypertrophy in a chronic kidney disease mice model." (PMID 32733380, 2020).
chronic kidney disease (continued). "An increase in the FGF23 level is recognized in the pathogenesis of secondary hyperparathyroidism with low 1,25(OH)2D3, hyperphosphatemia, and hypocalcemia in patients with advanced chronic kidney diseases." (PMID 32708317, 2020). "Importantly, chronic kidney disease, which eventually progresses to cardiovascular disease, is characterized by reduced Klotho levels and FGF23 up-regulation." (PMID 32640692, 2020). "FGF23 is also elevated when renal function declines, and peaks in end-stage renal disease." (PMID 32294899, 2020). "The analyses were performed with data from 1793 patients in whom 24-h urine protein and phosphate, serum phosphate, FGF23, and klotho levels were measured simultaneously, obtained from the KoreaN cohort study for Outcome in patients With Chronic Kidney Disease (KNOW-CKD)." (PMID 32569271, 2020). "EPO stimulated FGF23 production in mouse and human, increasing serum FGF23 and reducing serum phosphate, and may contribute to elevated FGF23 in chronic kidney disease patients receiving EPO." (PMID 33330462, 2020). "The Paracalcitol and ENdothelial fuNction in chronic kidneY disease (PENNY) study showed that paricalcitol reduced serum PTH (−75.1 pg/mL, 95% CI −90.4 to −59.8; p < 0.001) and its action is linked to increased FGF23 levels ( + 107 pg/mL, 95% CI 44 to 170; p = 0.001)." (PMID 32204545, 2020). "Osteocytic sclerostin and FGF23 expression are highly upregulated in chronic kidney disease." (PMID 32733380, 2020). "This study was however unable to associate phosphorus intake with odds of elevated FGF23 expression in the cohort, in the absence of chronic kidney disease." (PMID 32982966, 2020). "Since promoting renal phosphate excretion is among the main functions of FGF23, and since abnormalities in calcium-phosphate homeostasis are prominent in patients with chronic kidney disease (CKD), it seems plausible that FGF23 is involved in deregulated phosphate homeostasis in these patients." (PMID 32857288, 2020). "During chronic kidney disease, FGF23 is upregulated in osteocytes and released into blood." (PMID 32309615, 2019). "Although FGF-23 is an early biomarker in the development of chronic kidney disease (CKD), this may occur as a compensatory response, in order to restore vitamin D levels and hyperphosphaturic effect." (PMID 31295336, 2019). "This could be an intriguing point, since chronic kidney disease patients, who are burdened by an overwhelming degree of vascular calcification, also have very high levels of FGF23, which could act as a promoter of MSC differentiation toward OB/OS cells." (PMID 30791553, 2019). "Chronic kidney disease patients show increasing serum FGF-23 concentrations as disease worsens." (PMID 30911673, 2019). "The role of emerging factors like FGF-23 and Klotho in cardiovascular risk in both the early and late stages of chronic kidney disease is not entirely understood." (PMID 30934737, 2019). "In light of these findings, the main pathophysiological consequence of the downregulation of Klotho observed in acute and chronic renal failure may be the induction of renal FGF23 resistance." (PMID 29851418, 2018). "Increased FGF23 levels may be one of the earliest detectable markers of chronic kidney disease, prior to changes in calcium, phosphorous, or even parathyroid hormone (PTH)." (PMID 29633705, 2018). "FGF-23 is increased in inflammatory bowel disease and chronic kidney disease (CKD)." (PMID 29946298, 2018). "The role of FGF23 in chronic kidney disease is established best: Plasma FGF23 is elevated before a marked decrease of glomerular filtration rate (GFR), and it exhibits a strong positive correlation with mortality, hypertrophy of the left ventricle, and disease progression." (PMID 29807981, 2018). "Furthermore, it has been shown that FGF23 is high in patients with chronic kidney disease (CKD) and can be extremely high in some subjects with end-stage renal disease (ESRD)." (PMID 29515522, 2018).
chronic kidney disease (continued). "In patients with and without chronic kidney disease, enhanced circulating FGF23 levels associate with pathologic cardiac remodeling, i.e., left ventricular hypertrophy (LVH) and myocardial fibrosis and increased cardiovascular mortality." (PMID 29892269, 2018). "A high plasma FGF23 level has been found in patients with various acute and chronic disorders including renal (acute kidney injury, chronic kidney disease), cardiovascular (coronary heart disease, myocardial infarction, atrial fibrillation), inflammatory, and metabolic diseases." (PMID 29807981, 2018). "Plasma levels of FGF23 are increased in patients with chronic kidney disease." (PMID 29073196, 2017). "FGF23 has been associated with a number of human diseases, including X-linked hypophosphatemia (XLH), autosomal dominant hypophosphatemic rickets (ADHR), chronic kidney disease (CKD), familial tumoral calcinosis, McCune-Albright syndrome, and fibrous dysplasia of bone." (PMID 27784318, 2016). "Identification of the different signaling pathways for these two actions of FGF23 may have important clinical significance in patients with chronic kidney disease (CKD)." (PMID 26588476, 2015). "Prior studies examining the association of FGF23 with markers of inflammation and insulin resistance were limited by a focus on chronic kidney disease (CKD) populations, small sample size and/or lack of race and sex diversity." (PMID 25811862, 2015). "Therefore, we examined the relationship between RDW and both intact and C-terminal FGF23 as well as the ratio between the two, and the difference between cFGF23 and iFGF23, in a cohort of patients with chronic kidney disease and chronic heart failure." (PMID 26079688, 2015). "To date, FGF23 has mainly been studied in chronic disease, particularly in chronic renal failure." (PMID 26491212, 2015). "Prior studies have shown that FGF23 concentrations are associated with markers of inflammation and insulin resistance but they have been limited by a focus on persons with chronic kidney disease (CKD) and lack of race and sex diversity." (PMID 25811862, 2015). "Considering increasing FGF-23 levels with the progression of chronic kidney disease, its effects on the mineral metabolism, and possible relationship with the development of cardiovascular disease, it is thought that FGF-23 might be a prognostic factor." (PMID 25295189, 2014). "It was shown that serum FGF-23 levels increased before PTH began to rise in chronic kidney disease." (PMID 25295189, 2014). "If extrapolated to humans, our data would predict that in situations where circulating concentrations of both aldosterone and intact FGF23 are elevated, such as in chronic kidney disease, aldosterone may amplify the effects of FGF23 on Na+ retention." (PMID 24797667, 2014). "Circulating FGF23 concentrations are increased 2 to 5-fold above the normal range early in the course of kidney disease, but can reach 100-fold above normal levels in the end-stage renal disease." (PMID 24015259, 2013). "After an induction phase, a stable model of renal impairment was obtained (target urea range 80–100 mg/dL), mimicking several aspects of chronic kidney disease - mineral and bone disorder including secondary hyperparathyroidism, bone abnormalities and pathological elevation of FGF23." (PMID 23718816, 2013). "In patients with end-stage renal disease, FGF23 may exert a toxic effect on the cardiovascular system in a Klotho-independent manner." (PMID 23455471, 2013). "Determining the FGF23 responsive genes in the kidney in the setting of chronic kidney disease is challenging because of the systemic effects resulting from FGF23 regulation of phosphate and vitamin D homeostasis and the intrinsic abnormalities related to kidney disease process." (PMID 22970174, 2012).
chronic kidney disease (continued). "Elevations of circulating FGF23 also occur early in the course of chronic kidney disease (CKD), where it stimulates phosphaturia to maintain phosphate balance and contributes to the development of secondary hyperparathyroidism through suppression of 1,25(OH)2D levels." (PMID 22970174, 2012). "FGF23 is also markedly elevated in patients with end stage renal disease (ESRD)." (PMID 22970174, 2012). "High FGF23 levels in patients with chronic kidney disease are due to the declining renal clearance and also may represent a compensatory response to hyperphosphataemia." (PMID 22121479, 2012). "We also identified renal gene products that may mediate a direct effect of FGF23 to accelerate the progression of chronic kidney disease." (PMID 22970174, 2012). "The goal of this study was to measure FGF-23 levels in critically ill patients with acute kidney injury to determine whether FGF-23 levels were elevated, as in chronic kidney disease." (PMID 21906363, 2011). "FGF-23 levels are elevated or inappropriately normal in patients with tumor-induced osteomalacia and several inherited hypophosphatemic disorders, but the most significant increases are found in patients with chronic kidney disease (CKD)." (PMID 20593414, 2010). "Although there are fewer studies examining the effects of the kidney and chronic kidney disease (CKD) on cartilage, fibroblast growth factor 23 (FGF23) has emerged as a significant factor linking bone metabolism with renal calcium and phosphorus metabolism." (PMID 40538811, 2025). "Initially, studies were performed on patients with Chronic Kidney Disease (CKD)—as CKD progresses, phosphate excretion declines, leading to a compensatory rise in FGF-23 serum levels to maintain phosphate balance." (PMID 40137447, 2025). "Expression of Klotho decreases gradually during the progression of chronic kidney disease (CKD), while the FGF23 levels increase." (PMID 40165603, 2025). "Experimental evidence suggests that in individuals with chronic kidney disease (CKD), elevated FGF-23 levels diminish calcitriol synthesis and contribute to the activation of the RAAS, potentially leading to increased renin production." (PMID 39989455, 2025). "We describe the case of a 72-year-old man with chronic kidney disease (CKD) 3b due to hypertensive nephrosclerosis, noted to have persistent hypophosphatemia and mildly elevated fibroblast growth factor-23 (FGF-23)." (PMID 41583152, 2025). "However, in conditions of FGF23 excess, such as in chronic kidney disease (CKD), FGF23 may cross the BBB and potentially disrupt CNS function." (PMID 41007258, 2025). "There are also reports that FGF23 is a pleiotropic hormone, as it additionally exhibits effects on receptors located in the heart and may contribute to cardiovascular mortality and left ventricular hypertrophy in chronic kidney disease." (PMID 40649786, 2025). "Given the role of FGF23 in the pathogenesis of chronic kidney disease, the protein has been investigated as a potential biomarker of osteoporosis in patients with CKD or end-stage renal disease (ESRD)." (PMID 41367909, 2025). "FGF-23 was also associated with death in non-dialysis chronic kidney disease stages 3–5 patients." (PMID 40136613, 2025). "Interpretation of FGF23 concentrations can be challenging, especially in patients with FGF23-independent renal hypophosphatemia who have experienced a decrease in glomerular filtration (e.g., patients with Fanconi syndrome and chronic kidney disease in the course of cystinosis)." (PMID 41008628, 2025). "Moreover, plasma FGF23 is correlated with outcomes in chronic kidney disease." (PMID 39887469, 2025). "Moreover, higher levels of FGF23 have been strongly linked with an increased mortality risk in hemodialysis patients; a finding that was later replicated in various chronic kidney disease (CKD) and non-CKD populations." (PMID 40237064, 2025).
chronic kidney disease (continued). "In patients with chronic kidney disease (CKD), SGLT2 inhibitors have been associated with alterations in bone and mineral metabolism, including increased serum phosphate, fibroblast growth factor-23 (FGF-23), and parathyroid hormone (PTH) levels, along with decreased 1,25-dihydroxyvitamin D levels." (PMID 40517274, 2025). "It has been demonstrated that in patients with chronic kidney disease (CKD), the FGF23 cleavage process decreases as the glomerular filtration rate declines." (PMID 40869274, 2025). "In healthy people, plasma phosphate (P), 1,25-dihydroxyvitamin D (1,25(OH)2D) and PTH are the main regulators of plasma FGF23, but from early stages of chronic kidney disease (CKD), FGF23 increases before an increase in plasma P is observed." (PMID 38770543, 2024). "However, it has been suggested that inhibition of FGF23 improves inflammation in mice with chronic kidney disease in vivo and that blocking FGF23 activity could be a therapeutic target to reduce inflammation." (PMID 39009650, 2024). "Another growth factor, FGF23, is known to rise in response to inflammation and hypoxia and can contribute to the development of chronic kidney disease (CKD)." (PMID 38932130, 2024). "Fibroblast growth factor 23 (FGF23) is a bone-derived hormone that plays a central role in chronic kidney disease-mineral bone disorder and is associated with CKD progression and cardiovascular morbidity." (PMID 37752381, 2024). "Fibroblast growth factor-23 (FGF-23) and Klotho have been proven to contribute to chronic kidney disease-mineral and bone disorder (CKD-MBD) in patients undergoing hemodialysis." (PMID 39839279, 2024). "Chronic kidney disease (CKD) leads to alterations in fibroblast growth factor 23 (FGF23) and the renal-bone axis." (PMID 38770543, 2024). "However, a study by Hanks and colleagues with 1040 participants reported a positive association between insulin resistance and FGF23 levels in the absence of chronic kidney disease." (PMID 38732094, 2024). "Notwithstanding, the intricate interplay among FGF23, parathyroid hormone, and 1α,25-dihydroxy-vitamin D holds significance in the context of a pathological condition known as mineral and bone disorder, which occurs in individuals with chronic kidney disease (CKD-MBD)." (PMID 38970663, 2024). "FGF23 has been well characterized as a prognostic marker in chronic kidney disease (CKD) due to its impact on phosphate homeostasis, in addition to exerting pro-inflammatory effects." (PMID 37763754, 2023). "During the early stages of chronic kidney disease (CKD), serum fibroblast growth factor-23 (FGF-23) increases to prevent hyperphosphatemia." (PMID 37152972, 2023). "This study provides potential biomarkers for the early detection of hearing impairment complicated by chronic renal failure, and the reduction of FGF23/D-serine may provide a potential target for the treatment of hearing impairment complicated by chronic renal failure." (PMID 36649363, 2023). "In addition, clinical studies in ESRD patients and non-ESRD chronic kidney disease patients show that high plasma levels of FGF23 are associated with an increased infection rate compared to patients with lower titers." (PMID 36828412, 2023). "Fibroblast growth factor 23 (FGF‐23) is a phosphaturic hormone used for monitoring of chronic kidney disease (CKD) in humans." (PMID 38053473, 2023). "Fibroblast growth factor 23 (FGF-23) is a bone-derived protein that acts as a regulator in phosphate and vitamin D homeostasis and is elevated in patients with chronic kidney disease (CKD)." (PMID 36790465, 2023). "On the other hand, in people suffering from chronic kidney disease (CKD), FGF23 concentrations are increased." (PMID 35665817, 2023). "The Fibroblast growth factor 23 (FGF23)/α-klotho axis is heavily impaired in chronic kidney disease (CKD)." (PMID 36221075, 2022).